LAMA5 (laminin subunit alpha 5)
Diseases named in the same sentence as LAMA5 in open-access papers (continued):
Sharing a sentence is not in itself a finding about the gene and the disease.
microhematuria (2 papers, 2019 to 2023). "The proband inherited the COL4A5 variant from the mother, as expected for X-linked inheritance, who only presented with microscopic hematuria, and the LAMA5 variant from the father who had microscopic hematuria and unilateral hypoacusia." (PMID 37761826, 2023). "The LAMA5 variant was also identified in the proband’s father who presented with microhematuria in line with a digenic pattern of transmission as also suggested by the biparental contribution." (PMID 30808327, 2019). "Proband’s father in family 2, harboring the single LAMA5 mutation displays constant microhematuria suggesting that damaging LAMA5 mutations in a heterozygous state could alone explain familial hematuria." (PMID 30808327, 2019). "Recently an association of LAMA5 and COL4A5 variants has been described in four family members presenting with microhematuria and proteinuria and progressive ESRD in the spectrum of ATS." (PMID 30808327, 2019).
non-small cell lung carcinoma (2 papers, 2005 to 2020). A group of at least three distinct histological types of lung cancer, including non-small cell squamous cell carcinoma, adenocarcinoma, and large cell carcinoma. "Finally, all growth factors were shown to downregulate the expression of LAMA5, which is interesting as a reduced level of LAMA5 has been shown to be associated with an increased tendency to develop lymph node metastasis in non-small-cell lung cancer." (PMID 15846300, 2005).
Renal cyst (2 papers, 2018 to 2019). A fluid filled sac in the kidney. "In line with previous reports renal cysts were also observed in family 1 affected members who harbor the combination of LAMA5/COL4A4 mutations." (PMID 30808327, 2019). "Unique pathognomonic findings from kidney biopsies such as renal cysts and podocytes foot processes fusion or retraction should be regarded as hallmark of a LAMA5/COL4 variants coinheritance." (PMID 30808327, 2019). "Despite the fact that Lama5 mouse knockouts are fatal, mice with a hypomorphic Lama5 mutation (Lama5neo) that reduces laminin α5 expression, exhibit proteinuria, hematuria and cystic kidneys." (PMID 29764427, 2018).
atherosclerosis (1 paper, 2025). A disease characterized by the build-up of fatty material and calcium deposition in the arterial wall resulting in partial or complete occlusion of the arterial lumen. "In atherosclerosis, ECs communicated extensively with pericyte cells and SMCs through LAMININ (LAMA5-(ITGA1+ITGB1), LAMA5-(ITGA7+ITGB1), LAMB2-(ITGA6+ITGB4), LAMB2-(ITGA6+ITGB1)) and COLLAGEN (COL4A1-(ITGA1+ITGB1), COL4A2-(ITGA1+ITGB1)) pathways." (PMID 40225569, 2025).
ciliopathies (1 paper, 2013). "However, mice in which Lama5 has been disrupted develop Polycystic Kidney Disease (PKD), a phenotype comorbid with LR asymmetry defects caused by ciliopathies." (PMID 24068947, 2013).
Cushing syndrome (1 paper, 2025). Cushing's syndrome (CS) encompasses a group of hormonal disorders caused by prolonged and high exposure levels to glucocorticoids that can be of either endogenous (adrenal cortex production) or exogenous (iatrogenic) origin. "Furthermore, LAMA5 is also one of the potential therapeutic targets for heart disease in patients with depression/Cushing's syndrome/exogenous glucocorticoid supplementation." (PMID 40642838, 2025).
depression (1 paper, 2025). "To further explore the diagnostic value of cortisol and LAMA5 for cardiac function in patients with depression, we conducted ROC and correlation analyses in patients of the control group, DP with HF group, and DP without HF group." (PMID 40642838, 2025). "The patients we collected with depression comorbid with HF also had various underlying heart diseases, which introduced interference with the plasma levels of LAMA5." (PMID 40642838, 2025). "Moreover, the potential of LAMA5 is validated as a biomarker for myocardial hypertrophy and impaired cardiac function in patients with depression." (PMID 40642838, 2025). "It is notable that, in contrast to BNP, LAMA5 does not exhibit a significant increase in HF patients without depression, indicating that LAMA5 is not a universal biomarker for myocardial hypertrophy or HF." (PMID 40642838, 2025).
developmental delays (1 paper, 2022). "In this study, the patients with biallelic LAMA5 variants presented focal seizures and developmental delays, suggesting a potential role of LAMA5 in epilepsy with the involvement of neurodevelopment." (PMID 35663266, 2022).
endometriosis (1 paper, 2022). The growth of functional endometrial tissue in anatomic sites outside the uterine body. "More recently, another study concluded that there is an association of a LAMA5 (rs2427284) SNP with advanced stages of endometriosis (III/IV)." (PMID 35204508, 2022).
epilepsy (1 paper, 2022). A brain disorder characterized by episodes of abnormally increased neuronal discharge resulting in transient episodes of sensory or motor neurological dysfunction, or psychic dysfunction. "The establishment of the association between LAMA5 and epilepsy will facilitate the genetic diagnosis and management in patients with infant epilepsy." (PMID 35663266, 2022). "The present study suggests that recessive LAMA5 variants were potentially associated with infant epilepsy." (PMID 35663266, 2022). "The association between LAMA5 and epilepsy was supported by multiple pieces of evidence, such as common clinical features, unique gene functions, and statistical evidence." (PMID 35663266, 2022). "In this study, we investigated the association between LAMA5 and epilepsy." (PMID 35663266, 2022). "Recessive LAMA5 variants were potentially associated with infant epilepsy." (PMID 35663266, 2022). "Therefore, this study provided direct evidence in supporting the association between LAMA5 and epilepsy." (PMID 35663266, 2022). "This study revealed LAMA5 as a potential novel autosomal recessive gene in infant epilepsy, enriching the genetic etiology of epilepsy." (PMID 35663266, 2022).
familial nephropathy (1 paper, 2022). "These facts raise doubts about whether LAMA5 G3685R is a heterozygous LAMA5 variant responsible for familial nephropathy with FSGS." (PMID 36173685, 2022).
Fuchs endothelial corneal dystrophy (1 paper, 2024). Fuchs endothelial corneal dystrophy (FECD) is the most frequent form of posterior corneal dystrophy (see this term) and is characterized by excrescences on a thickened Descemet membrane (corneal guttae), generalized corneal edema, with gradually decreased visual acuity. "A multi-ancestry GWAS meta-analysis of Fuchs endothelial corneal dystrophy identifies eight novel loci, including low-frequency missense variants in laminin genes LAMA5 and LAMB1, and phenome-wide scans uncover pleiotropy with renal traits at TCF4." (PMID 38582945, 2024).
head and neck cancer (1 paper, 2022). A primary or metastatic malignant neoplasm affecting the head and neck. "In head and neck cancer, the mutation of laminin alpha 5 (LAMA5) gene can increase the expression of YY1." (PMID 35791393, 2022).
hematoma (1 paper, 2019). A hematoma is a collection of blood from a vascular structure into an extravascular space. "Furthermore, the knockdown of Nr4a1 significantly increased the expression of p-NF-κB p65, IL-1β, TNF-α, and MMP-9 with a decrease of ZO-1, occludin, and Lama5 in the peri-hematoma tissue." (PMID 31660977, 2019).
Kidney Cyst (1 paper, 2018). Abnormal fluid filled sac within the kidney, either acquired or congenital. "The cystic phenotype overlaps with that of a mouse model, which carried a Lama5 hypomorphic mutation that caused severely reduced Lama5 protein levels and produced kidney cysts." (PMID 29764427, 2018).
Lambert-Eaton myasthenic syndrome (1 paper, 2023). Lambert-Eaton myasthenic syndrome (LEMS) is an autoimmune, presynaptic disorder of neuromuscular transmission characterized by fluctuating muscle weakness and autonomic dysfunction frequently associated with small-cell lung cancer (SCLC). "SYT2-CMS, SNAP25-CMS, VAMP1-CMS, UNC13A-CMS, RPH3A-CMS, and LAMA5-CMS are characterized by defects in the SNARE complex, and phenotypically similar to Lambert-Eaton myasthenic syndrome (LEMS)." (PMID 36835142, 2023).
liver diseases (1 paper, 2022). "The persistently affected genes Lama5, Gtse1, Fabp4, and Bcl6 possess the potential to be therapeutic targets for liver disease induced by AFB1." (PMID 35783385, 2022). "The persistently affected Lama5, Gtse1, Fabp4 and Bcl6 gene can be potential target genes for the treatment of AFB1 induced liver diseases, but their effectiveness needs to be further explored in experiments." (PMID 35783385, 2022).
liver fibrosis (1 paper, 2024). "Importantly, PI3K-AKT and focal adhesion-related proteins, such as PDGFRβ, PIKR3R1, ITGB5, COL1A1, COL6A1, COL6A3, and LAMA5, are mainly associated with liver fibrosis." (PMID 38469403, 2024).
mucinous colorectal adenocarcinoma (1 paper, 2023). "and proteins involved in ECM organization, including DDR1, LAMA5, and TTR, were upregulated in mucinous colorectal adenocarcinoma." (PMID 37158593, 2023).
Myocardial fibrosis (1 paper, 2025). "Notably, inhibiting CORT reduced myocardial fibrosis in CMS rats, but LAMA5 knockdown did not." (PMID 40642838, 2025).
myocardial infarction (1 paper, 2024). Gross necrosis of the myocardium, as a result of interruption of the blood supply to the area, as in coronary thrombosis. "LAMA1, LAMA3 and LAMA5, other laminins, are targets of the approved drug lanoteplase, used in the treatment of myocardial infarction but with unknown mechanisms of action." (PMID 38383672, 2024).
Nephropathy (1 paper, 2022). A nonspecific term referring to disease or damage of the kidneys. "Regarding the limitations of this study, this variant, LAMA5 V3687M, was found in only 1 pedigree, although we confirmed its responsibility for nephropathy with FSGS and lung deformity in heterozygous and homozygous KI mice." (PMID 36173685, 2022). "We discovered a possibly novel heterozygous variant in the LAMA5 gene, which might lead to slowly progressive nephropathy with FSGS and pulmonary structural deformity, possibly through compromised cell adhesion." (PMID 36173685, 2022).
Obesity (1 paper, 2008). Accumulation of substantial excess body fat. "Drosophila LanA is closely related to human LAMA5 gene, which maps to the well-replicated obesity-linkage region on chromosome 20q13.2-q13.3." (PMID 18694491, 2008).
ovary (1 paper, 2022). "Notably, high LAMA5 expression in tumors negatively impacted the survival of patients with gastric, lung and ovary tumors." (PMID 35267534, 2022).
pancreatic adenocarcinoma (1 paper, 2022). "So there is a lower average methylation of cpg markers associated with LAMA5 and higher average expression of LAMA5 in pancreatic adenocarcinoma (PAAD) compared to normal tissue." (PMID 35360846, 2022).
pancreatic tumor (1 paper, 2022). "Interestingly, using mass spectrometry we also identified LAMA5 to be a highly elevated protein in EVs isolated from a mouse pancreatic tumor line (ACB, unpublished) that is used extensively as an orthotopic murine model of PDAC70." (PMID 35241737, 2022).
preeclampsia (1 paper, 2025). Preeclampsia is a hypertensive disorder of pregnancy that is characterized by new-onset hypertension with proteinuria presenting after 20 weeks of gestation, and depending on mild or severe forms may initially present with severe headache, visual disturbances, and hyperreflexia. "RT‒qPCR analysis confirmed the upregulation of FKBP5, LAMA5, FZD5 and FGG mRNA expression in preeclampsia." (PMID 40490753, 2025).
prostate carcinoma (1 paper, 2016). A carcinoma that arises from epithelial cells of the prostate gland. "LAMA5 has also been reported to be cleaved by membrane-type 1 MMP (MMP14), a transmembrane protease that can promote the cell migration of prostate cancer cells via cleavage of LAMA5 in laminin-1047." (PMID 27324842, 2016).
rheumatoid arthritis (1 paper, 2024). A chronic, systemic autoimmune disorder characterized by inflammation in the synovial membranes and articular surfaces. "KEGG pathway analysis of the upregulated proteins in ENTPD1+CD55+ cells indicated enrichment for proteins involved in rheumatoid arthritis (e.g., HLA-DRA, ICAM1) and ECM–receptor interaction (e.g., type I collagen, Laminin subunit alpha-5, integrin-subunit alpha-6)." (PMID 38612896, 2024).
schizophrenia (1 paper, 2023). A major psychotic disorder characterized by abnormalities in the perception or expression of reality. "Among highly ranked genes lacking SFARI Gene scores and OMIM annotations, previous studies suggest association with NDDs and schizophrenia [OBSCN, PLEC, RYR2, ZSWIM8], cortical formation and thickness [LAMA5, GOLGA3), and neurodegenerative diseases (PKHD1, DNAH1]." (PMID 35596027, 2023).
sickle cell anemia (1 paper, 2023). "BCAM1 has also been shown to be phosphorylated by glycogen synthase kinase 3β, casein kinase II and PKA at serines 596, 598 and 621, respectively and the phosphorylation state of BCAM might be a critical factor for adhesion of erythrocytes to LAMA5 in sickle cell anemia." (PMID 36647260, 2023).
skin aging (1 paper, 2024). The gradual irreversible changes in structure of skin that occur as a result of the passage of time.. "Clearly, delving into the regulation of the LAMA5 gene in the context of skin aging holds significant interest." (PMID 39199288, 2024).
teratoma (1 paper, 2020). A non-seminomatous germ cell tumor characterized by the presence of various tissues which correspond to the different germinal layers (endoderm, mesoderm, and ectoderm). "Lama4 expression was on the same level in both types of teratomas, whereas Lama5 and Lamb2 expression was significantly lower in Pax7−/− teratomas." (PMID 32552916, 2020).
toxoplasmosis (1 paper, 2019). A parasitic disease contracted by the ingestion or fetal transmission of toxoplasma gondii.
triple-negative breast carcinoma (1 paper, 2022). An invasive breast carcinoma which is negative for expression of estrogen receptor (ER), progesterone receptor (PR), and human epidermal growth factor receptor 2 (HER2). "Subsequently, it was shown that 1,25(OH)2D and BXL0124 downregulated the pluripotency markers OCT4, CD44, and laminin subunit alpha 5 (LAMA5) in the mammospheres of a triple-negative breast cancer (TNBC) cell line." (PMID 35328609, 2022).
tumor (41 papers, 2016 to 2025). "Top 10 candidates also included proteins associated with tumor progression (LAMA5, SDCBP, TENA, PTPRJ, MUC16, TAOK1; see “Discussion”)." (PMID 35241737, 2022). "We identify LAMA5 specifically as a key promotor of liver metastasis growth and find that the inhibition of tumour-derived LAMA5 reduced branching angiogenesis in association with increased Notch signalling in tumour endothelia." (PMID 31064120, 2019). "Tumor-derived EVs were enriched in proteins associated with vesicular transport and tumorigenesis, including Laminin subunit alpha 5 (LAMA5), Syntenin-1 (SDCBP), and Tenascin (TENA), all of which are implicated in cancer progression, metastasis, and exosome biogenesis." (PMID 41149854, 2025). "Interestingly, the blood vessels in LAMA5sh tumours also displayed a significant reduction in perfusion, indicating that LAMA5 loss significantly altered functional aspects of tumour vessels as well as their morphology." (PMID 31064120, 2019). "However, although vascular normalisation has been reported to sensitise tumours to chemotherapy through improved tumour perfusion and thereby drug delivery, we found reduced perfusion upon LAMA5 loss." (PMID 31064120, 2019). "While BCAM appears to have tumour‐suppressive effects on single cells, it promotes the dispersion of OC cell spheroids by regulating LAMA5‐integrin‐β1‐dependent compaction and thereby facilitating invasion of metastatic target sites." (PMID 36647260, 2023). "Within the pancreas, we see significantly higher expression of LAMA5 in tumor cells compared with adjacent normal pancreas followed by the lowest expression in stroma cells." (PMID 35360846, 2022). "The role of five of them (LAMB2, SERPINEE1, ITGB1, TNC, and LAMA5) in tumor growth has been well established." (PMID 35642785, 2022). "The present work shows that SOD3 triggers the transcription of the gene encoding laminin α4 (LAMA4) but represses that of the gene coding for laminin α5 (LAMA5) in ECs in vitro and in vivo, thus changing the laminin α4/laminin α5 ratio in tumor blood vessels." (PMID 35267534, 2022). "Using the GTEx database, we can look at the RNA expression levels reported for LAMA5 across tissue type or specifically in the pancreas or tumor." (PMID 35360846, 2022). "Lama5 gene plays a role in promoting angiogenesis during tumor development and is a key promoter of liver metastatic growth." (PMID 35783385, 2022). "Tumor-infiltrating myeloid cells can drive tumor cells to express Lama5 through NF-κB gene transduction, thereby promoting angiogenesis." (PMID 35783385, 2022). "The tumor-specific epigenetic features displayed for LAMA5 in PDOs 11 and 18 are also mirrored at the protein level by 3D immunofluorescence analysis, with active and repressed chromatin profiles associated to protein presence or loss, respectively." (PMID 33879786, 2021). "Here, we demonstrate the tumour cell-specific expression of laminin chains α5, β1 and γ1 (LAMA5, LAMB1 and LAMC1 respectively) in orthotopic human liver metastases from mice and the deposition of these laminin chains within the tumour stroma." (PMID 31064120, 2019). "Human LAMA5, LAMB1 and LAMC1 transcripts were identified in orthotopic metastases, a finding supported by immunohistochemical analysis demonstrating the expression of the human LAMA5 protein in these tumours." (PMID 31064120, 2019). "Our data firmly supports this and implicates tumour-derived LAMA5 as a regulator of endothelial Notch signalling." (PMID 31064120, 2019). "It has been reported that Lu binds to Lama5 competitively with Integrinα3β1/α6β1 and promotes tumor cell migration by modulating Integrin-mediated cell attachment to Laminin-511 protein." (PMID 30059007, 2018). "Additionally, laminin subunit alpha-5 was uniquely identified in T1 tumors, suggesting a role in early tumor invasion and basement membrane remodeling." (PMID 40430030, 2025).